FGF9 (fibroblast growth factor 9)
Diseases named in the same sentence as FGF9 in open-access papers (continued):
Sharing a sentence is not in itself a finding about the gene and the disease.
tumor (continued). "Although various immune cells also produce these cytokines and chemokines, FGF9-producing fibroblasts may constitute a microenvironment that facilitates hepatic fibrosis and tumor growth through induction of local inflammation." (PMID 31862949, 2019). "The contradiction between the relationship of FGF9 expression and prognosis in different Lauren type might be interpreted as distinct molecular properties and tumor progression between intestinal- and diffuse-type gastric adenocarcinoma." (PMID 30646925, 2019). "Likewise, the expression of FGF9 in lymph node metastatic site tumor cells was also connected with Lauren type." (PMID 30646925, 2019). "Moreover, FGF9 neutralizing antibody was added into CAF-CM to treat GC cells so as to further clarify the effect of FGF9 in CAFs on tumor cell migration and invasion." (PMID 30646925, 2019). "In addition, two features were characterized by FGF9 positive staining in lymph node metastasis sites: First, FGF9 staining was high in CAFs but low in tumor cells and this distribution was more remarkable in intestinal-type than in diffuse-type tumor." (PMID 30646925, 2019). "Therefore, FGF9 overexpression in PCa cells augments the formation of reactive stroma in the tumor microenvironment and promotes PCa initiation and progression." (PMID 30761180, 2019). "Moreover, the prevalence of FGF9 high-expression group was significantly increased in CAFs than that in tumor cells not only in primary tumor but also in lymph node metastatic sites (30.0% vs 11.9%, P < 0.01 and 32.1% vs 12.3%, P < 0.01, respectively)." (PMID 30646925, 2019). "We further examined the effect of FGF9 on tumor growth in vivo using a human tumor xenograft model." (PMID 31862949, 2019). "The results showed that the FGF9 expression level was higher and more common in CAFs than that in tumor cells, which was present not only in primary tumors but also in lymph node metastatic sites, indicating that FGF9 was mainly secreted by CAFs rather than by cancer cells." (PMID 30646925, 2019). "In brief, these results indicated that miR-214 could inhibit the tumor-promoting ability of CAFs via directly targeting FGF9 in vitro." (PMID 30646925, 2019). "Together this suggests that FGF9, as the target gene of miR-26a, may promote tumour growth and inhibit GC apoptosis." (PMID 27166269, 2016). "It's reported that miR-26a inhibits tumour growth by the target of FGF9 in GC." (PMID 27166269, 2016). "In the present study, using both mouse primary and tumor Leydig cells, we further explored how FGF9 could activate JNK, p38, ERK1/2, and Akt, which are the downstream signal transduction mediators of the Ras/MAPK and PI3K pathways." (PMID 24603862, 2014). "It is possible that opposite effects were FGF-dependent (FGF2 for the oncogenic effect and FGF9 for the tumor suppressive effect), the role of FGF2 being supported by previous studies (for example) but more work is needed to test the dependency of FGFR3 to FGFs." (PMID 23902722, 2013). "Except for fibroblast growth factor 9, none of them have been associated with response of tumor cells to cytostatic drugs." (PMID 23935662, 2013). "The observed correlation between high expression of FGF9 and short patient survival may indicate functional roles of FGF9 in tumor progression." (PMID 21853123, 2011). "Interestingly, FGFR1 signaling in DU 145 cells with the KLF5KR mutant was more sensitive to FGF9, implying that an endogenous pathway in the tumor cells could be involved in the activation of FGFR1 signaling." (PMID 38781024, 2024). "Consistent with our hypothesis, the subcutaneous xenograft tumors with FGF9 overexpression in nude mice exhibited an aggressive growth pattern of tumor nodules, and these changes were significantly suppressed upon XAV‐939 administration, as shown by the decreased tumor volume and weight." (PMID 37566761, 2023).
tumor (continued). "Thus, FGF9 may contribute significantly to increases in the tumour mass by elevating not only proliferation of HCC cells but also by supporting neovascularization." (PMID 32378800, 2020). "On the other, the effects of CAFs on the migration and invasion of GC cells could be significantly inhibited by adding FGF9-neutralizing antibody into the conditioning medium, suggesting the indispensable role of FGF9 in the tumor-promoting ability of CAFs in GC." (PMID 30646925, 2019). "Thus, miR-140 suppression of Fgf9 may not only be important for the development of lung and other tissues, but it may also function as an important tumor suppressor to ensure the quiescence of Fgf9 in adult tissues." (PMID 25978641, 2015). "Therefore, we set out to test the hypothesis that a microenvironmental change (i.e.hypoxia) in cancer development triggers FGF9 protein expression and that the overexpressed FGF9 promotes tumor progression." (PMID 24334956, 2014). "By binding to FGFR1, FGF9 activated FAK, AKT and ERK/MAPK signaling pathways to promote tumor cell proliferation and epithelial-mesenchymal transformation (EMT), thereby enhancing tumor cell migration and invasion." (PMID 40526701, 2025). "Deacetylated KLF5 promoted tumor cells to secrete TNF-α, which stimulated inflammatory CAFs to release FGF9." (PMID 38781024, 2024). "Tumours showed dependence on fibroblast growth factor (FGF), and production of FGF9 from CAFs resulted in multiple adenocarcinoma-like tumour nodules." (PMID 38920685, 2024). "In such cases, low expression of miR-214 in the tumor microenvironment increases chemokine (C-C motif) ligand 5 and fibroblast growth factor 9 (FGF9), which contributes to tumor growth and motility." (PMID 34846108, 2021). "Findings show that FGF2 is secreted from CAFs and contributes to tumor cell growth by stimulating synthesis of more collagen and the secretion of inflammatory cell-recruiting cytokines via CAFs expressed TGFβ, MMP7, and FGF9." (PMID 34203430, 2021). "FGF9 binds to FGFR3 IIIb or IIIc and enhances cell line migration by inducing gaps in monolayers of blood or lymphatic endothelium, similar to tumor invasion into the circulation." (PMID 33802841, 2021). "The overexpression FGF7, FGF9, FGF14, FGF18 and IGF1 genes was found significant in early tumor grades." (PMID 34061869, 2021). "Three genes, including B2M, FGF9 and HMGA1, were also found in the 30 upregulated (in tumor MF) gene list." (PMID 34831413, 2021). "By contrast, SLIT2, EFNB2, FGF9, and HEY1, which promote tumor angiogenesis, were downregulated in 9F-treated HCT116 cells." (PMID 32106543, 2020). "Previously, we demonstrated that FGF9 signaling through FGFR2-stimulated cell proliferation and tumor growth in MA-10 cells." (PMID 33172093, 2020). "Specifically, a novel mechanism was proposed that CAFs-derived miRNA-214 through targeting FGF9 in itself to regulate the EMT event of tumor cells, highlighting the crosstalk between tumor cells and TME." (PMID 30646925, 2019). "This study showed that miR-214 inhibited the tumor-promoting effect of CAFs on GC through targeting FGF9 in CAFs and regulating the EMT process in GC cells, suggesting miRNA-214/FGF9 in CAFs as a potential target for therapeutic approaches in GC." (PMID 30646925, 2019). "The expression of FGF9 was separately analyzed in primary tumor CAFs (PTCAF-FGF9), primary tumor cell (PT-FGF9), lymph node metastatic site CAFs (LNCAF-FGF9), and tumor cells in lymph node metastatic sites (LNT-FGF9)." (PMID 30646925, 2019). "The results further revealed reduced FGF9 and CCND2 staining intensities in xenograft tumors in the miR-4317 agomir group compared with the NC group, indicating a decrease in tumor cell proliferation in response to the downregulation of miR-4317." (PMID 30227870, 2018). "In IGF2-low tumors, other growth factors (FGF9, PDGFA) are more expressed than in IGF2-high tumors, suggesting that they play a compensatory role in tumor progression." (PMID 25089899, 2014).
tumor (continued). "Parallel to those studies, we showed that FGF9 also activated the phosphorylation of JNK, ERK1/2, and/or p38 in mouse primary and tumor Leydig cells." (PMID 24603862, 2014). "Also, the model showed increased levels of TAMs and transforming growth factor beta (TGF-β), MMP7, FGF9, and FGF2 in the tumour niche." (PMID 38920685, 2024). "CAFs in GC have been found to secrete cytokines, such as CXCL12, interleukin 11 (IL-11), stromal-derived factor 1 (SDR1), and fibroblast growth factor 9 (FGF-9), to promote epithelial–mesenchymal transition (EMT), the key initiator of tumor invasion and metastasis." (PMID 35557959, 2022). "Transfecting human fibroblast growth factor 9 (FGF-9) cDNA into mouse BALB/c 3T3 clone A31 cells could lead to morphological transformation of the cells, formation of foci, soft agar growth and tumor formation within nude mice." (PMID 33234721, 2020). "We previously also reported that FGF9 bound and activated FGFR2 to promote the ERK1/2 and Rb/E2F1 pathways, and subsequently increased the expression of cyclins and CDKs to enhance cell proliferation and tumor growth both in vitro and in vivo." (PMID 33172093, 2020). "Targeting the MAPK signal transduction pathway through the targeting of the FGF2, FGF9, MECOM, PLA2G4C and PRKACB might increase tumor responsiveness to irinotecan treatment." (PMID 28749961, 2017). "We examined FGF9 expression in 180 GC and corresponding non-tumorous gastric tissue samples by immunohistochemistry and evaluated its role in predicting tumour prognosis." (PMID 27166269, 2016). "FGF9 with higher expression remained a notable indicator of shorter survival in stage II (30.6 months vs. 64.9 months, P < 0.001, n=56) and stage III (29.7 months vs. 58.9 months, P < 0.001, n=92) by tumour stage stratification in GC." (PMID 27166269, 2016). "Regarding the clinicopathological features, none of the parameters ─ age, gender, tumor location, histological type, or tumor stage ─ had a significant relationship to FGF9 expression." (PMID 25925261, 2015). "In addition, we confirmed that increased FGF9 promoted the tumor formation in another animal model, in which the liver‐specific FGF9 transgenic mice feeding with HFHC diet only without CCl4 treatment." (PMID 37566761, 2023). "However, increased FGF9 expression in liver alone did not induce tumor formation and hardly mimic the tumor formation in the HFHC diet and CCl4 treatment model in our study." (PMID 37566761, 2023). "The immunohistochemical expression of FGFR1-4 was increased in the FGF9/PBS group and decreased in the groups treated with cordycepin whether the tumor was exposed to FGF9 or not." (PMID 33172093, 2020). "Nevertheless, whether CAF-derived FGF9 was also involved in tumor progression was not delineated by these studies." (PMID 30646925, 2019). "On the basis of the discovery that miR‐372‐3p was overexpressed and FGF9 was underexpressed compared with adjacent tissues in three LSCC cell lines, we hypothesize that FGF9 seemed to be the tumor suppressor and miR‐372‐3p might act as a tumor facilitator in LSCC." (PMID 28440022, 2017). "In conclusion, targeting the MAPK signal transduction pathway through the targeting of FGF9, FGF2, MECOM, PRKACB and PLA2G4C might increase tumor responsiveness to irinotecan and improve patient survival thus being therapeutically and prognostic significant in CRC patients." (PMID 28749961, 2017). "We observed a tendency between age and FGF9 expression levels in GC patients (χ2 = 5.634, P = 0.018), but no significance was found between FGF9 expression level and other clinicopathological variables, including gender, site, TNM, tumour size, nodal status, metastasis status and tumour invasion." (PMID 27166269, 2016). "Hepatocyte‐specific FGF9 transgenic mice (FGF9Alb) fed with a HFHC diet without CCl4 treatment exhibited an increased hepatic ECM and tumor burden." (PMID 37566761, 2023).
tumor (continued). "In an analysis of 80 paired tumor and adjacent nontumor tissue samples, FGF9 and CCND2 expressions were significantly elevated in tumor tissues compared to adjacent nontumor tissues." (PMID 30227870, 2018). "Seven days after tumor inoculation, mice were randomly assigned to receive the intratumoral (i.t.)injection of 5 ng FGF9, BSA (the vehicle control for FGF9) or no treatment (Control), and intraperitoneal (i.p.)injection of 20 mg/kg cordycepin or PBS (the vehicle control for cordycepin)." (PMID 33172093, 2020). "However, we found that FGF9 was underexpressed in LSCC tissues, which suggested its tumor suppressor role rather than a tumor facilitator role." (PMID 28440022, 2017).
cancer (53 papers, 2007 to 2026). A tumor composed of atypical neoplastic, often pleomorphic cells that invade other tissues. "FGF9 is over-expressed in cancer-associated fibroblasts (CAFs) and mediates communication with cancer cells." (PMID 38391921, 2024). "The involvement of FGF7 and FGF9 secreted by cancer-associated fibroblasts were also demonstrated to promote migration and invasion of GC cells." (PMID 30082912, 2019). "Our data demonstrate that FGF9 IRES functions as a cellular switch to turn FGF9 protein synthesis ‘on’ during hypoxia, a likely mechanism underlying FGF9 overexpression in cancer cells." (PMID 24334956, 2014). "FGF9 has been implicated in the pathogenesis of cancer through its high-affinity receptor FGFR3c." (PMID 38391921, 2024). "Aberrant activation of FGF9/FGFR signaling is associated with cancers." (PMID 38391921, 2024). "The abnormal activation of FGF9 is associated with many cancers." (PMID 37570275, 2023). "C12, highly expressed ACTA2, VIM, and FGF9, was recognized as cancer-associated fibroblasts (CAFs)." (PMID 35523772, 2022). "A previous study showed that FGF9 from cancer-associated fibroblasts may activate invasion ability of GC cells." (PMID 27166269, 2016). "To date, the antiapoptotic genes OLFM4, SIRT1, PIM-1, and DOCK3, the tumor suppressor PTEN, the cell proliferation and invasion genes CITRON and CLDN10, and FGF9 expressed by cancer-associated fibroblasts have been reported as potential targets for miR-486/miR-486-5p in malignant disease." (PMID 26895105, 2016). "Several studies have linked dysregulated FGF9 in various cancers." (PMID 27166269, 2016). "Abnormal expression of FGF9 has been associated with several human cancers and endometriosis." (PMID 24334956, 2014). "FGF9, as a target gene of miR-214, could suppress cancer-associated fibroblasts (CAFs) in GC cells." (PMID 35190498, 2022). "It would be interesting to study if the R108E mutant of FGF9 suppresses cancer proliferation by inhibiting FGF9 signaling (e.g., through FGFR3) in future studies." (PMID 38391921, 2024). "FGF9 has oncogenic activity and is involved in the progression of cancers in the lung, stomach, colon, testis, and ovary." (PMID 38391921, 2024). "This indicates that FGF9 is a major therapeutic target in cancer, and antagonists to FGF9 must be developed." (PMID 38391921, 2024). "Since FGF9 has oncogenic activity and is overexpressed in many cancers (see Introduction), FGF9 R108E should be useful as a potential therapeutic." (PMID 38391921, 2024). "Dominant-negative FGF9 R108E mutant would be a potential therapeutic and useful to study the role of FGF9 in cancer." (PMID 38391921, 2024). "Fibroblast growth factor 9 (FGF9) is involved in serial types of cancer; however, the specific role of FGF9 in NASH‐driven HCC is not fully understood." (PMID 37566761, 2023). "Se-Y is an antioxidant with cancer prevention effects, and BMP2, FGF9, and HEY1 are a class of genes associated with the cancer pathway." (PMID 37570275, 2023). "And the expression of HD5 mediated by FGF9 signaling pathway further verified HD5 was correlated with cancer." (PMID 35190498, 2022). "FGF9 has carcinogenic activities, which support a function for its increase in the pathogenesis of several cancers." (PMID 33234721, 2020). "We next used a C57BL/6J mouse model to confirm the anti-cancer effect of cordycepin on FGF9-induced testicular tumorigenesis." (PMID 33172093, 2020). "Through cancer bioinformatics and experimental analyses, FGF9 was found to be upregulated in MIBC tissues." (PMID 33234721, 2020). "FGF9’s involvement in malignant neoplasms has been reported in glioma, ovarian cancer, and lung cancer." (PMID 30720727, 2019). "In other words, FGF9 was only positive in especially high-grade cancer cells in cases with localized PCa." (PMID 30720727, 2019).